EVPLL (envoplakin like)
Tractability: PROTAC: ubiquitination databases record sites on it.
Gene: Protein-coding gene on chromosome 17 (18,377,674 to 18,389,652, forward strand). Ensembl gene ENSG00000214860.
Subcellular location (Human Protein Atlas): Nuclear bodies; Nucleoplasm
Gene Ontology:
Biological process: intermediate filament cytoskeleton organization
Genetic constraint (gnomAD): Loss-of-function variants: 39 observed, 29.69 expected, observed/expected ratio (o/e) 1.31, 90% interval 1.02 to 1.71. The upper end of that interval is the gene's LOEUF score, 1.71, which puts it in group 6 of 6, group 1 being the genes least tolerant of losing a copy. Missense variants: 376 observed, 318.59 expected, observed/expected ratio (o/e) 1.18, 90% interval 1.08 to 1.28. Synonymous variants: 154 observed, 123.65 expected, observed/expected ratio (o/e) 1.25, 90% interval 1.09 to 1.42.
Homologues: Orthologues: tropical clawed frog evpl (43% identical), zebrafish evpla (37% identical). Paralogues in human: EVPL (71% identical), PPL (28% identical).